Y_RNA (Y RNA )
Gene: Miscellaneous RNA gene on chromosome 14 (51,253,933 to 51,254,023, reverse strand). Ensembl gene ENSG00000201820.
Homologues: Orthologues: chimpanzee Y_RNA (97% identical), macaque Y_RNA (86% identical). Paralogues in human: RNY4 (87% identical), RNY4P6 (86% identical), RNY4P9 (85% identical), RNY4P13 (84% identical), RNY4P19 (82% identical), RNY4P37 (82% identical), RNY4P7 (82% identical), RNY4P29 (81% identical), Y_RNA (81% identical), RNY4P10 (80% identical), RNY4P17 (80% identical), RNY4P23 (80% identical), and 85 more.